PAPSS2 (3'-phosphoadenosine 5'-phosphosulfate synthase 2)
Description:
Bifunctional enzyme with both ATP sulfurylase and APS kinase activity, which mediates two steps in the sulfate activation pathway. The first step is the transfer of a sulfate group to ATP to yield adenosine 5'-phosphosulfate (APS), and the second step is the transfer of a phosphate group from ATP to APS yielding 3'-phosphoadenylylsulfate/PAPS, the activated sulfate donor used by sulfotransferases. In mammals, PAPS is the sole source of sulfate while APS appears to only be an intermediate in the sulfate-activation pathway. Plays indirectly an important role in skeletogenesis during postnatal growth.
Synonyms: SK2; ATPSK2; BCYM4
Tractability: Small molecule: a structure with a bound ligand is known; it has a high-quality binding pocket. PROTAC: ubiquitination databases record sites on it; its protein half-life has been measured.
Target class: Enzyme; Transferase
Gene: Protein-coding gene on chromosome 10 (87,659,613 to 87,747,708, forward strand). Ensembl gene ENSG00000198682.
Subcellular location (Human Protein Atlas): Mitochondria
Pathways (Reactome):
Metabolism: Metabolism of ingested H2SeO4 and H2SeO3 into H2Se; Transport and metabolism of PAPS
Disease: Defective PAPSS2 causes SEMD-PA
Gene Ontology:
Molecular function: protein binding; adenylylsulfate kinase activity; nucleotidyltransferase activity; sulfate adenylyltransferase (ATP) activity; ATP binding
Biological process: 3'-phosphoadenosine 5'-phosphosulfate biosynthetic process; hormone metabolic process; sulfate assimilation
Cellular component: cytosol; nucleus
Genetic constraint (gnomAD): Loss-of-function variants: 44 observed, 49.57 expected, observed/expected ratio (o/e) 0.89, 90% interval 0.7 to 1.14. The upper end of that interval is the gene's LOEUF score, 1.14, which puts it in group 5 of 6, group 1 being the genes least tolerant of losing a copy. Missense variants: 613 observed, 720.52 expected, observed/expected ratio (o/e) 0.85, 90% interval 0.8 to 0.91. Synonymous variants: 256 observed, 268.78 expected, observed/expected ratio (o/e) 0.95, 90% interval 0.86 to 1.06.
Homologues: Orthologues: chimpanzee PAPSS2 (99% identical), macaque PAPSS2 (97% identical), pig PAPSS2 (95% identical), rabbit PAPSS2 (95% identical), dog PAPSS2 (94% identical), mouse Papss2 (93% identical), rat Papss2 (92% identical), guinea pig PAPSS2 (91% identical), tropical clawed frog papss2 (83% identical), zebrafish papss2b (81% identical), zebrafish papss2a (77% identical), Drosophila melanogaster Papss (63% identical), and 1 more. Paralogues in human: PAPSS1 (77% identical).
Diseases named in the same sentence as PAPSS2 in open-access papers:
PAPSS2 is named in the same sentence as 47 diseases in open-access papers, as found by Europe PMC text mining. Sharing a sentence is not in itself a finding about the gene and the disease. The quoted sentences say what the papers report.
spondyloepimetaphyseal dysplasia (9 papers, 2012 to 2023). An osteochondrodysplasia that results in abnormalities of bone growth in the vertebral column, epiphysis, and metaphysis. "Inactivating mutations for PAPSS2 are associated with severe inherited developmental skeletal disorders, Kanshin Beck disease, spondyloepimetaphyseal dysplasia in humans, and brachymorphism in mice." (PMID 22916269, 2012). "In addition to Brachyolmia, earlier mutations of PAPSS2 have also been reported in patients suffering from spondyloepimetaphyseal dysplasia (SEMD) Pakistani type, which was later on reclassified as Brachyolmia type 4." (PMID 36421772, 2022). "Mutations in PAPSS2 cause an autosomal recessive form of spondyloepimetaphyseal dysplasia (SEMD), Pakistani type [OMIM:612847], in humans, whereas a point mutation in the adenosine 5'-phosphosulfate kinase region of Papss2 causes brachymorphism (bm) in mice." (PMID 22394585, 2012). "PAPSS2 plays significant roles in androgen excess, bone dysplasia, and spondyloepimetaphyseal dysplasia when disrupted." (PMID 37036370, 2023). "The defection of PAPSS2 can lead to alarming bone development diseases, containing malformation, spondyloepimetaphyseal dysplasia, hepatocellular carcinoma, estrogenic hormone disorder, and so on." (PMID 36685893, 2022). "At present, the mechanisms by which the PAPSS2 gene affects participation in leisure-time physical activity are not known, but mutations in it cause spondyloepimetaphyseal dysplasia, a disease characterized by short stature and limbs in both mice and humans." (PMID 36901996, 2023). "A truncation mutation of the human PAPSS2 gene was reported in a Pakistani family suffering from a novel form of spondyloepimetaphyseal dysplasia (SEMD)." (PMID 22916269, 2012).
brachyolmia (7 papers, 2015 to 2025). Brachyolmia is a rare, clinically and genetically heterogeneous group of bone disorders characterized by short trunk, mild short stature, scoliosis and generalized platyspondyly without significant abnormalities in the long bones. "We report a Chinese boy with brachyolmia caused by a novel compound heterozygous mutation in the PAPSS2 gene." (PMID 40927400, 2025). "We are reporting that the Brachyolmia in this family is caused due to a missense mutation in the PAPSS2 gene." (PMID 36421772, 2022). "This quick review of the literature of patients with different ethnic backgrounds confirms that the mutation in PAPSS2 can lead to an autosomal recessive form of Brachyolmia." (PMID 36421772, 2022). "Previously, it has been documented that mutations in PAPSS2 lead to a functional loss in the PAPSS2 proteins which leads to multiple types of skeletal abnormalities in patients suffering from Brachyolmia." (PMID 36421772, 2022). "Loss-of-function mutations in PAPSS2 are associated with autosomal-recessive forms of brachyolmia, a heterogeneous group of skeletal dysplasias, including the Hobaek (OMIM 271530) and Toledo (OMIM 271630) types." (PMID 34093655, 2021). "During the present investigation, we have used WES to identify and report a homozygous mutation in PAPSS2 that caused an autosomal recessive form of Brachyolmia in an enrolled consanguineous Pakistani family with affected subjects exhibiting a reduced height and skeletal abnormalities." (PMID 36421772, 2022). "PAPSS2 mutation might present a gradation of the phenotypic spectrum from brachyolmia to spondylo-epiphyseal and spondylo-epimetaphyseal dysplasia of the Pakistani type." (PMID 34539746, 2021). "There are already few studies that are available in literature regarding patients from different ethnic backgrounds that have established thatmutations in the PAPSS2 gene can result in the autosomal form of Brachyolmia." (PMID 36421772, 2022). "Till now, PAPSS2 was known to cause SEMD, Pakistani type/Brachyolmia with main clinical characteristics of disproportionate short stature, short spine, kyphosis, scoliosis, enlarged knee joints, bowed legs, irregular epiphyses, narrow carpal space, and mild brachydactyly." (PMID 35261200, 2022).
colitis (6 papers, 2022 to 2024). Inflammation of the colon. "PAPSS2 encodes an enzyme that mediates the sulfation of numerous cellular proteins, including the mucins that form a protective layer of the intestinal epithelium; loss of PAPSS2 has been shown to promote colitis and colon cancer." (PMID 38001126, 2023). "Intestinal sulfation, crucial for colitis protection, is dependent on the host PAPS synthase 2 (PAPSS2), which is central in generating PAPS, the universal sulfonate donor for sulfation." (PMID 39152482, 2024). "Since the expression of Papss2 and the abundance of mucin sulfation exhibited reduced expression in murine colitis, exploring its expression profile in patients with IBD holds substantial significance." (PMID 39068517, 2024). "Mice deficient in Papss2 display reduced intestinal sulfomucin content and heightened sensitivity to DSS-induced colitis." (PMID 39068517, 2024). "The PAPSS2-PAPS-sulfation axis plays an essential role in colitis and colonic carcinogenesis." (PMID 37296884, 2023). "Mechanistically, IAA upregulated the expression of key molecules 3’-phosphoadenosine 5’-phosphosulfate synthase 2 (Papss2) and solute carrier family 35 member B3 (Slc35b3) involved in mucin sulfation via AHR, thereby enhancing intestinal barrier function and ameliorating colitis." (PMID 39068517, 2024).
polycystic ovary syndrome (6 papers, 2015 to 2024). A disorder that manifests as multiple cysts on the ovaries. "In humans, PAPSS2 pathogenic variants originate several disorders including skeletal dysplasia, androgen excess, and polycystic ovary syndrome." (PMID 38249632, 2024). "Mutations found in the PAPSS2 gene result in severe disease states such as bone dysplasia, androgen excess and polycystic ovary syndrome." (PMID 35463959, 2022). "Heterozygosity for PAPSS2 mutations can be associated with a phenotype resembling polycystic ovary syndrome." (PMID 25594860, 2015). "The seminal case of PAPSS2 deficiency was a girl with early-onset androgen excess who clinically presented with premature adrenarche at the age of 6 years, thereafter progressing to a polycystic ovary syndrome (PCOS)–like phenotype in adolescence." (PMID 31294783, 2019). "The few patients identified with mutations in this gene are female, and heterozygous inactivation of PAPSS2 has been associated with polycystic ovary syndrome, premature puberty, hyperandrogenic anovulation, very low DHEA-S levels, and increased androgen levels." (PMID 30009155, 2018). "Among these symptoms are bone and cartilage dysplasia, as well as androgen excess and polycystic ovary syndrome (PCOS), all caused by point-mutations in the PAPSS2 gene encoding for the PAPS synthase 2 enzyme." (PMID 35463959, 2022). "Disruption of DHEA sulfation due to inactivating mutations in the human gene encoding PAPSS2, a crucial cofactor of SULT2A1, has been shown to result in increased androgen activation and a polycystic ovary syndrome (PCOS) phenotype in both homozygous and heterozygous individuals." (PMID 27003302, 2016).
prostate carcinoma (5 papers, 2015 to 2024). A carcinoma that arises from epithelial cells of the prostate gland. "Previous studies reported the frequent loss of the PAPSS2-PTEN locus in prostate cancer and its association with prostate-specific antigen reoccurrence in patients." (PMID 37984988, 2024). "Of particular relevance to prostate cancer, two mutations in PAPSS2 have been reported as causing androgen excess via complete (W362Cfs*3) or partial (G270D) disruption of DHEA sulfation." (PMID 26485759, 2015). "Based on the correlation between the copy number losses of PTEN, FAS, PAPSS2 and PSA recurrence and with the current quest for an improved biomarker, it is recommended that the molecular function and translational implication of PTEN, FAS, and PAPSS2 loss in prostate cancer are further investigated." (PMID 25679447, 2015). "Lastly, we observed that the frequency of the PAPSS2-PTEN locus deletion significantly increased in prostate cancer patients with radiation therapy." (PMID 37984988, 2024). "PAPSS2 is also commonly lost along with PTEN in prostate cancer xenografts." (PMID 34178034, 2021). "In addition, we draw attention to PAPSS2, which holds important biological functions that may increase our understanding of the biology of PSA recurrence and prostate cancer relapse." (PMID 25679447, 2015).
breast carcinoma (4 papers, 2015 to 2022). "Nevertheless, the enhanced PAPSS2 is vital to push migration and metastasis of breast cancer cells and shows shorter relapse-free survival periods in cancer of the breast." (PMID 36685893, 2022). "Moreover, TGFβ signaling regulates the expression of 3′-phosphoadenosine 5′-phosphosulfate synthase 2 (Papss2), a gene related to breast cancer cell migration." (PMID 35565312, 2022). "PAPSS2 is critical for breast cancer cell migration and metastasis." (PMID 34323415, 2021).
osteochondrodysplasia (4 papers, 2012 to 2021). A term referring to disorders characterized by abnormalities in the development of bones and cartilage. "PAPSS2 is needed for sulfation of extracellular matrix molecules during bone development; deficiencies result in osteochondrodysplasias." (PMID 34205844, 2021).
colon cancers (3 papers, 2022 to 2024). "A recent study showed that expression of PAPSS2 gene is decreased in the colon cancers of mice and humans, and deletion of PAPSS2-PAPS made mouse models more susceptible to malignant transformation." (PMID 37296884, 2023). "Most recently, it has been described that PAPSS2 is decreased in colon cancers in mice and humans, correlating with a worse survival due to an increased intestinal permeability and bacteria infiltration." (PMID 38540220, 2024). "In one study, the authors propose that intestinal sulfation may represent a potential diagnostic marker, and PAPSS2 may serve as a potential therapeutic target for IBD and colon cancer." (PMID 37296884, 2023).
lung squamous cell carcinoma (3 papers, 2019 to 2024). "For example, 13–45% of the 100 most down-regulated genes in HAP1 were also deregulated in prostate adenocarcinoma, lung squamous cell carcinoma, and skin cutaneous melanoma when comparing patients with and without the PAPSS2-PTEN locus deletion." (PMID 37984988, 2024).
arthrosis (2 papers, 2012 to 2024). "Given the premature development of degenerative knee joint disease in the mutant mice and other similarities between SEMD mice and human lacking normal PAPSS2 activity, it has been proposed that this mutant represents a model of human PAPSS2 deficiency-associated arthrosis." (PMID 22916269, 2012). "Humans lacking normal PAPSS2 activity exhibit long bone shortening and bowing, and also show degenerative joint disease, including evidence of knee joint arthrosis." (PMID 22916269, 2012).
colorectal cancer (2 papers, 2009 to 2024). A primary or metastatic malignant neoplasm that affects the colon or rectum. "Additionally, the diminished expression of Papss2 is correlated with poorer survival rates in colorectal cancer patients, indicating its potential significance beyond IBD." (PMID 39068517, 2024). "In this study, we identified PAPSS2, TUBG2, NTRK2, B4GALT1 and OSMR as genes harboring cancer-specific promoter methylation in human colorectal cancer." (PMID 19662090, 2009).
lung carcinoma (2 papers, 2019 to 2024). "Similarly, the genes PAPSS2 and ITPRIP have been recognized as unfavourable prognostic factors across a spectrum of cancers, including thyroid, colorectal and lung cancers." (PMID 38894657, 2024).
Barrett adenocarcinoma (1 paper, 2021). An adenocarcinoma arising from Barrett metaplastic epithelium in the esophagus. "Loss of PAPSS2 at 10q22 is associated with poor prognosis in patients with resected Barrett’s adenocarcinoma and other gastroesophageal junction cancers." (PMID 34178034, 2021).
chronic myelogenous leukemia (1 paper, 2024). "Because we found that up to 30% of the HAP1 cell clones showed a deletion of the PAPSS2-PTEN locus without stressors applied and considering that HAP1 cells originated from chronic myelogenous leukemia, we further investigated the occurrence of this deletion across cancer types using patient data." (PMID 37984988, 2024).
Cirrhosis (1 paper, 2024). A chronic disorder of the liver in which liver tissue becomes scarred and is partially replaced by regenerative nodules and fibrotic tissue resulting in loss of liver function. "When individual subjects and cells were considered, PAPSS2 expression in enterocytes and goblet cells was lower in the advanced decompensation group versus the other cirrhosis patients." (PMID 38369527, 2024).
glioma (1 paper, 2018). A benign or malignant brain and spinal cord tumor that arises from glial cells (astrocytes, oligodendrocytes, ependymal cells). "Therefore, PAPSS-1 and PAPSS-2 provided abundant PAPS substrate for sulfotransferases which leads to the increase of pAp production in gliomas." (PMID 30283018, 2018).
spondyloepiphyseal dysplasia (1 paper, 2019). An osteochondrodysplasia that results in abnormalities of bone growth in the vertebral column and the epiphysis.